SIRT1 (sirtuin 1)
Diseases named in the same sentence as SIRT1 in open-access papers (continued):
Sharing a sentence is not in itself a finding about the gene and the disease.
Insulin resistance (continued). "At certain doses, biochanin-A reduced glucose tolerance and insulin resistance, developed insulin sensitivity and increased SIRT-1 expression which might explain the anti-diabetic properties of the drug." (PMID 38106650, 2023). "Moreover, PKCδ promotes downregulation of SIRT1, which is also related to insulin resistance, leading to liver damage and fibrosis." (PMID 36810903, 2023). "Interestingly, lycopene activates SIRT1 to impart muscle angiogenesis and reverse insulin resistance in models of age-related vascular decline." (PMID 36678315, 2023). "In addition, scientists showed that resveratrol triggers SIRT1 in mammalian tissues and triggers muscle SIRT1 in animals with diet-induced insulin resistance." (PMID 37241737, 2023). "Most importantly, a number of drugs used for treatment of diverse asthma, sepsis, liver injury, insulin resistance, postmenopausal osteoporosis, Parkinson’s disease, diabetic nephropathy and cancers exert their effects through modulation of non-coding RNAs/SIRT1 axis." (PMID 37441551, 2023). "The activation of SIRT1 may improve insulin resistance by accelerating fatty acid oxidation, the deacetylation of PGC-1α, and the activation of PPAR-α in skeletal muscle." (PMID 37108143, 2023). "Consequently, the administration improved insulin resistance by activating the AMPK/SIRT1/PGC-1α pathway in the skeletal muscle of db/db mice." (PMID 37488560, 2023). "Additionally, the effects of berberine in amelioration of hepatic insulin resistance have been revealed to be mediated through regulation of miR-146b/SIRT1 axis." (PMID 37441551, 2023). "Additionally, Sirt-1 overexpression protects against metabolic abnormalities via high-fat diets and insulin resistance in diabetic animals." (PMID 37512578, 2023). "In traditional Chinese medicine formula, Yunpi Heluo Decoction can activate autophagy by regulating the SIRT1-FoxO1 signaling pathway in skeletal muscle, while improving lipid metabolism, attenuating insulin resistance and exerting a protective effect on pancreatic β cells." (PMID 37810881, 2023). "In this study, SE and SV administration improves insulin resistance by activating mitochondrial function through the activation AMPK/SIRT1/PGC-1α pathway and reducing oxidative stress, which increases muscle fiber size and alleviates degenerated fibers in db/db mice." (PMID 37488560, 2023). "While SIRT1 decreases with increasing body fat, sclerostin expression increases in parallel with adipose tissue and insulin resistance, and promotes adipocyte hypertrophy and the differentiation of bone precursors into white adipocytes, reducing bone formation." (PMID 35267956, 2022). "Moreover, DEL-1 acts locally to attenuate palmitate- and HFD-induced skeletal muscle ER stress and insulin resistance via SIRT1/SERCA2-mediated signaling." (PMID 35909571, 2022). "Here, we generated 1α(OH)ase-null mice (targeted ablation of the 25-hydroxyvitamin D 1α hydroxylase enzyme) and found that these mice developed hepatic glucose overproduction, glucose intolerance, and hepatic insulin resistance accompanied by reduced Sirtuin 1 (Sirt1) expression." (PMID 35132380, 2022). "SIRT1 gain-of-function mimics the PPARγ activation in alleviating insulin resistance." (PMID 35743009, 2022). "These novel findings indicate that Sirt1 reduction in the liver may be responsible for the hepatic insulin resistance and impaired glucose metabolism in the 1,25(OH)2D3-deficient mice." (PMID 35132380, 2022). "Administration of MOTSc in mice resulted in increased glucose uptake, primarily by skeletal muscle tissue, prevented the development of insulin resistance induced by a high-fat diet, and reversed age-associated insulin resistance via activation of AMPK and SIRT1." (PMID 35683389, 2022).
Insulin resistance (continued). "Due to this polyphenol’s antioxidant property and the possibility of its favorable effect on SIRT1 and Fetuin-A levels and reduced insulin resistance, this study aimed to investigate the effect of EA oral supplement on SIRT1, Fetuin-A, and insulin resistance in patients with type 2 diabetes." (PMID 33546744, 2021). "Berberine counteracts insulin resistance by activating two proteins, sirtuin 1 (SIRT1), an acetylase, and AMPK, as a result of activation of SIRT-1 and AMPK pathways, adiponectin concentration increases, and increasing adiponectin is associated with regulation of β oxidation and glucose metabolism." (PMID 34094026, 2021). "After confirming the Sirt1 and Sirt3 activation on systemic and cardiac insulin resistance, we wanted to know the effect of Sirt1 and Sirt3 activation on lipid parameters i.e., triglycerides, LDL, HDL, serum free fatty acids and total cholesterol in pre-diabetic rats fed with high fructose diet." (PMID 33668369, 2021). "There is an apparent correlation between SIRT1 and insulin resistance." (PMID 34753504, 2021). "In vitro evidence on the endothelial cell models of insulin resistance and hyperglycemia showed the ability of Magliocco to reduce reactive oxygen species (ROS) (p < 0.01) and cytokine release (p < 0.01) and to upregulate SIRT1 and SIRT6 (p < 0.01)." (PMID 34073604, 2021). "E6155 also is showed to directly bind to SIRT1 and it improves blood glucose tolerance and insulin resistance through stimulating glucose uptake in liver and muscle cells, with elevated adiponectin and AMPK (adenosine monophosphate-activated protein kinase) activation of diabetic mice." (PMID 34712151, 2021). "As Sirt1 and Sirt3 play an essential role in metabolic regulation, we were interested to evaluate the effect of Sirt1 and Sirt3 activation and their combination on fasting blood glucose levels and insulin resistance." (PMID 33668369, 2021). "In the context of insulin resistance, macrophage SIRT1 may play a beneficial role in regulating glucose homeostasis." (PMID 34099590, 2021). "SIRT1 overexpression also improves insulin resistance in part by targeting mitochondria." (PMID 33971886, 2021). "SIRT1 activation can increase the sensitivity of insulin and reduce insulin resistance." (PMID 33809718, 2021). "Furthermore, the drug telmisartan ameliorates insulin resistance in muscle cells by activating the AMPK/SIRT1 pathway in diabetic mice." (PMID 33806509, 2021). "A large body of evidence suggests that SIRT-1 regulates glucose and lipid metabolism, in addition to inflammatory responses, gluconeogenesis, and the levels of reactive oxygen species, which together contribute to the development of insulin resistance." (PMID 34149611, 2021). "Overall, the present investigation demonstrates that calystegines from Hyoscyamus albus provide cytoprotection to the HepG2 cells against insulin/glucose induced insulin resistance and apoptosis due to the regulation of SIRT1/Foxo1/G6PC/mTOR and NF-κB/JNK/TLR4 signaling pathways." (PMID 34034759, 2021). "Furthermore, SIRT1 levels in the adipose tissue correlate negatively with insulin-resistance parameters and positively with adiponectin expression." (PMID 33806509, 2021). "Based on in vivo and in vitro results, we hypothesized that the SIRT1/FOXO1 pathway plays an important role in improving insulin resistance under MNAM treatment." (PMID 32280711, 2020). "AMPK and Sirt1 play important roles in lipid homeostasis and insulin resistance." (PMID 32467715, 2020). "Sirt1 also exerts a significant regulatory function in energy metabolism in response to nutrient stimulating signals, whereas p66Shc is currently regarded as a principal regulator of overnutrition-mediated insulin resistance." (PMID 32066482, 2020). "Therefore, SIRT1 can increase the insulin resistance via promoting oxidation of free fatty acid and biogenesis of mitochondria through deacetylation of PPAR-α and PGC-1α activation of skeletal muscles." (PMID 32815547, 2020).
Insulin resistance (continued). "In adipocytes, SIRT1 is required for the activation of AMPK to improve insulin resistance." (PMID 33390968, 2020). "Western blotting was used to detect whether inhibition of SIRT1 modulated the effect of MNAM on PA-induced insulin resistance via hepatocyte insulin signaling." (PMID 32280711, 2020). "Resveratrol activated Sirtuin 1 and unexpectedly prevented β‐cell dedifferentiation, rather than improving insulin resistance associated with a Westernized diet." (PMID 33312555, 2020). "Another study showed that BMSC-derived exosomes could modulate age-related insulin resistance by the transfer of functional exosomal miR-29b-3p and thereby inhibit the expression of the target gene SIRT1." (PMID 32019561, 2020). "In addition, APS treatment regulated SIRT1 pathway to improve insulin resistance and ameliorate mitochondria dysfunction." (PMID 31894851, 2020). "However, in patients receiving sildenafil (100 mg/d), higher expression of miR-22-3p proteins (associated with myocardial hypertrophy and its remodeling) and sirtuin 1 (SIRT1) (its overexpression reduces insulin resistance) was demonstrated." (PMID 33153226, 2020). "The role of adequate SIRT1 levels for proper liver function is well documented, as SIRT1 deletion results in hepatic steatosis and inflammation, and SIRT1 activators improve hepatosteatosis and insulin resistance." (PMID 32069846, 2020). "SIRT1 and adiponectin together operate to adjust the gluco-lipidic profile, to mediate the white adipose tissue browning and, most importantly, to antagonize insulin resistance, fatty liver diseases and inflammatory responses." (PMID 33202604, 2020). "SIRT1 is also correlated with inflammation and insulin resistance, which contributes to the development of a pro-tumoral environment, increasing the risk of ROS (reactive oxygen species) production, thus leading to DNA damage and mutations, genome instability, one of the hallmarks of carcinogenesis." (PMID 33123088, 2020). "Genetic ablation of Sirt1 in adipose tissues leads to increased adiposity and insulin resistance." (PMID 31618980, 2019). "Therefore, SIRT1 should be a pharmacological therapeutic target to treat insulin resistance and T2DM." (PMID 30972029, 2019). "However, there is still insufficient clinical data regarding the effect of SIRT1 activators on insulin resistance and T2DM." (PMID 30972029, 2019). "In addition, SIRT1 protein expression is reduced in skeletal muscle and primary myotubes derived from T2DM patients, suggesting that diminished SIRT1 contributes to insulin resistance induced by TNF-α in skeletal muscle." (PMID 30972029, 2019). "This is likely explained by the compelling evidence that SIRT1 overexpression offers substantial benefits on serum cholesterol and insulin levels and increased resistance to high-fat diet induced glucose intolerance and insulin resistance." (PMID 30131769, 2018). "Consequently, SIRT1 activators inhibit vacuolization, degeneration, and inflammation in the heart of patients with insulin resistance." (PMID 30246793, 2018). "Indeed, increased HDAC3 activity in PBMCs from T2DM patients has been directly correlated with inflammation and insulin resistance, and negatively with SIRT-1 level." (PMID 29330620, 2018). "In recently, SIRT1 also regulates adiponectin secretion and glucose production, several SIRT1 activators have been demonstrated to have beneficial effects on glucose homeostasis and insulin sensitivity in animal models of insulin resistance." (PMID 30320001, 2018). "Insulin differentially regulates AT and skeletal muscle SIRT1 expression in the short-term and circulating FFA elevation negates these effects, which may be associated with lipid-induced insulin resistance." (PMID 29417372, 2018). "Moreover, SIRT1 activation protects from insulin resistance and helps with glucose homeostasis in different insulin sensitive organs." (PMID 27659520, 2017).
Insulin resistance (continued). "Interestingly, SIRT1 regulates the key components of the circadian clock, CLOCK and BMAL1, and when circadian misalignment is induced in mice, reduced hepatic BMAL1 and SIRT1 levels and insulin resistance ensue." (PMID 29264533, 2017). "Since Sirt1 can reduce insulin resistance and treat type 2 diabetes." (PMID 28859155, 2017). "SIRT1, as one of the modulators in insulin resistance, is indispensable for learning and memory." (PMID 29164153, 2017). "In particular, SIRT1 activation is likely to be an important mediator for BCH-induced improvement in insulin resistance since SIRT1 inhibitor prevented BCH-induced beneficial effect on hepatic insulin resistance in HF/HFr-fed mice." (PMID 27874078, 2016). "A potential player in the relationship between inflammation and insulin resistance is SIRT1." (PMID 26904104, 2016). "Since SIRT1, by direct deacetylation of PPARγ, recruits the BAT program coactivator Prdm16 to PPARγ, it also plays a crucial role in the induction of genes typical for BAT and repression of visceral WAT genes associated with insulin resistance." (PMID 27104517, 2016). "Mice engineered to overexpress SIRT1 or mice that were treated with small-molecule activators of SIRT1, such as resveratrol, were protected from high-fat diet-induced liver steatosis and insulin resistance (15, –, 18)." (PMID 26655722, 2016). "Levels of SIRT1 are reportedly decreased with high-fat feeding and may therefore have a role in lipid-induced insulin resistance." (PMID 25798922, 2015). "Decreased expression of Nampt could participate in the development of hepatic steatosis and insulin resistance by reducing SIRT1 activity." (PMID 26232096, 2015). "Moreover, as SIRT1 also regulates inflammatory processes, adiponectin secretion or ROS formation, it indirectly contributes to the development of insulin resistance." (PMID 25786107, 2015). "Because increased SIRT1 expression or activation could improve insulin resistance and enhance insulin secretion through deacetylation and activation of PGC-1a." (PMID 24759758, 2014). "Overall, these strategies illustrate how the administration of NAD+ precursors constitutes an excellent tool to enhance SIRT1 activity in vivo and recapitulate the health benefits of SIRT1 overexpression, e.g. a strong protection against insulin resistance and increased oxidative capacity." (PMID 24567900, 2014). "Altogether, this renders the adipocyte-specific SIRT1 KO mice prone to develop insulin resistance." (PMID 24567900, 2014). "SirT1-dependent deacetylation of Lys268 and Lys293 is required to recruit the BAT program co-activator Prdm16 to Pparγ, leading to selective induction of BAT genes and repression of visceral WAT genes associated with insulin resistance." (PMID 25514854, 2014). "Hepatic overexpression and specific activation of SIRT1 ameliorates HFD-induced insulin resistance." (PMID 23880847, 2013). "Similarly, resveratrol, a SIRT1 activator, enhanced insulin sensitivity in vitro in a SIRT1-dependent manner and attenuated high-fat-diet-induced insulin resistance in vivo." (PMID 23442260, 2013). "Sirtuin-1 (SIRT1) is a potential therapeutic target to combat insulin resistance and T2D." (PMID 23878802, 2013). "In addition, the thyroid hormone metabolite T2 prevents insulin resistance through SIRT1 activation in HFD-fed rats." (PMID 23880847, 2013). "Here we aim to determine whether the therapeutic effects of AICAR against insulin resistance involve its anti-inflammatory function, which requires macrophage SIRT1." (PMID 23183898, 2012). "Similarly, treatment with different SIRT1 agonists prevents weight gain and insulin resistance when mice were challenged with high-fat diets." (PMID 23137106, 2012). "Indeed, resveratrol administration and accompanying activation of SIRT1 has improved health and survival of mice on a high-calorie diet by ameliorating insulin resistance." (PMID 22357324, 2012).
Insulin resistance (continued). "Sirt1 activation with resveratrol protected mice fed a high-fat diet against metabolic disease and insulin resistance, and treatment of adipocytes with Sirt1 activators increased glucose uptake and insulin sensitivity while Sirt1 knock down exerted the opposite effects." (PMID 22822451, 2012). "To investigate whether the therapeutic effects of AICAR against insulin resistance involve its anti-inflammatory function and work through macrophage SIRT1, we administrated AICAR to both MSKO and fl/fl control mice fed HF diets." (PMID 23183898, 2012). "In the present study, we intend to investigate whether the therapeutic effects of AICAR against insulin resistance involve its anti-inflammatory function, which requires macrophage SIRT1." (PMID 23183898, 2012). "This study was designed to test the hypothesis that the therapeutic effects of the AMPK agonist AICAR against insulin resistance involve its anti-inflammatory function, which requires macrophage SIRT1." (PMID 23183898, 2012). "The present study revealed that EA activated SIRT1, indicating that improved insulin resistance by EA may be attributed to enhanced SIRT1 expression." (PMID 20981161, 2011). "Moreover, overexpression of SIRT1 protects against insulin resistance in diabetic models and high-fat-diet-induced metabolic disorder." (PMID 20981161, 2011). "The inhibitory effects of SIRT1 on the NF-κB signaling pathway can significantly alleviate chronic inflammatory responses in tissues and exert important protective effects in metabolic diseases such as insulin resistance and atherosclerosis, as well as in inflammation-related diseases." (PMID 38745862, 2024). "Collectively, these findings suggest that hWJMSC-derived exosomes may mitigate HFD-induced metabolic dysfunction by reinforcing SIRT1-mediated metabolic processes, which consequently contributes to the protection against hepatic steatosis and insulin resistance." (PMID 39408777, 2024). "You Baiyang prepared an in-vitro and -vivo model of insulin resistance and found that SAL reduced insulin resistance; the mechanism may be that SAL activated the AMPK/SIRT1 signaling pathway to regulate mitochondrial quality control and ROS production and reduced insulin resistance." (PMID 38968273, 2024). "Genes such as sirtuin-1 (SIRT1), C-reactive protein (CRP), C-X-C motif chemokine receptor 2 gene (CXCR2), as well as chemokines and interleukins such as interleukin 12 (IL12A) and C-X-C motif chemokine ligand 8 (CXCL8), are strongly associated with insulin resistance and T2D." (PMID 38674857, 2024). "In addition, SIRT1 promotes insulin expression by activating the expression of NeuroD and MafA (Zhou, Tang & Chen, 2018) SIRT1 and its activators reduce insulin resistance and diabetic complications and are thus potentially effective therapeutic targets for type 2 diabetes (T2D)." (PMID 36815979, 2023). "It has been shown that SIRT1 and NF-κB activation have antagonistic activity in the regulation of metabolism (e.g., gluconeogenesis, glycolysis, fatty acid oxidation, and synthesis, oxidative phosphorylation, mitochondrial biogenesis, etc.)including insulin resistance and inflammation." (PMID 36672652, 2023). "We found that MOL supplementation markedly decreased the body weight, significantly upregulated the expression of Sirt1, FoxO1, PGC‐1α, IGF1, and substantially modulated the sex hormone level and improved insulin resistance, which may be associated with the relieves oxidative stress." (PMID 37701184, 2023). "Finally, activation of SIRT1 leads to insulin-stimulated translocation of GLUT4 storage vesicles (GSVs) from intracellular storage pools to the plasma membrane resulting in improvement of insulin resistance." (PMID 38027557, 2023). "Moreover, SIRT1 participates in the pathophysiological processes of oxidative stress, autophagy, ovulation disturbance and insulin resistance, which may be a vital link in the occurrence of PCOS." (PMID 36030228, 2022).